RN7SL482P (RNA, 7SL, cytoplasmic 482, pseudogene)
Gene: Miscellaneous RNA gene on chromosome 3 (66,323,855 to 66,324,152, forward strand). Ensembl gene ENSG00000241587.
Homologues: Orthologues: chimpanzee Metazoa_SRP (96% identical), macaque Metazoa_SRP (92% identical). Paralogues in human: RN7SL1 (82% identical), RN7SL2 (82% identical), RN7SL3 (81% identical), RN7SL296P (81% identical), RN7SL408P (80% identical), RN7SL122P (80% identical), RN7SL126P (80% identical), RN7SL15P (80% identical), RN7SL220P (80% identical), RN7SL664P (79% identical), RN7SL186P (79% identical), RN7SL448P (79% identical), and 704 more.